BCL2 (BCL2 apoptosis regulator)
Diseases named in the same sentence as BCL2 in open-access papers (continued):
Sharing a sentence is not in itself a finding about the gene and the disease.
tumor (continued). "In fact, miR-16 has been reported to act as a tumor-suppressive miRNA in many cancer types, and multiple apoptosis-related genes are targeted by miR-16, including BCL-2, CCND1, CCND3, and CCNE1." (PMID 26031775, 2015). "Tumor tissues from patients showing p-p38−/Bcl-2− and p-p38−/Bcl-2+ had higher OS than the other two subgroups (p = 0.001)." (PMID 26475474, 2015). "Consistent with results in vitro, YSC-ZDC increased Bax expression and inhibited Bcl-2 expression in tumor tissue." (PMID 26089933, 2015). "Bcl-xL and Bcl-2 are both important for tumor progression, and chemoresistance through interacting with pro-apoptotic BH3 proteins." (PMID 26204252, 2015). "In parallel, the Bcl-2 family proteins presented as Bax and Bak were elevated but Bcl-2 was reduced after administration of the DHM NDP combination in tumor cells." (PMID 25915649, 2015). "The one exception is BCL-2, which dramatically accelerates tumor development in the context of the Eμmyc mice." (PMID 26327622, 2015). "In a PANC-1 xenograft mouse model, we demonstrated that the combination of metformin and aspirin significantly inhibited tumor growth and downregulated the protein expression of Mcl-1 and Bcl-2 in tumors." (PMID 26056043, 2015). "In the present study, phosphorylation of PXN at Y31/118 is required for tumor invasion via increased Bcl-2 expression." (PMID 25826088, 2015). "Tumor suppressors miR-15a and miR-16 regulate tamoxifen sensitivity by targeting Bcl-2, miR-451 targets 14-3-3ζ, let7s target ER-α36, miR-375 targets metadherin and miR-200b/c target ZEB1." (PMID 26206152, 2015). "Apoptosis or tumor-related genes including, c-myc, Emp-1, bax, and bcl-2, play important roles in cell cycle progression, apoptosis, and cellular transformation." (PMID 26253141, 2015). "In summary, we provide evidence from cells, xenograft tumors, and human tumors to demonstrate that an increase in Bcl-2 protein stability due to its phosphorylation at Serine 87 is responsible for tumor progression and metastasis via increased MMP2 expression." (PMID 25826088, 2015). "In the human PCa tumour dataset, BCL-2 is up-regulated and is known to block chemotherapy induced apoptosis." (PMID 26553226, 2015). "Several anti-apoptotic proteins, such as Survivin and members of the Bcl family (Bcl-xl, Bcl-2 and Mcl-1) which are known to be crucial for tumor cell survival, are direct target genes of STAT3 and are down-regulated as a consequence of STAT3 inhibition." (PMID 26474284, 2015). "Second, VEGF induces activation of antiapoptotic genes, including bcl-2, which protect tumor cells from apoptosis." (PMID 25810565, 2015). "Arginine methyltransferase inhibitor 1 (AMI-1)strongly inhibited tumor growth, increased the ratio of Bax/Bcl-2, and induced apoptosis in mouse CRC xenograt model." (PMID 26078354, 2015). "The expression changes of apoptotic regulators such as Bcl2 and IAPs is an attractive strategy for exploring their role in raising the possibility of tumor cell apoptosis and thus defining potential therapeutic strategies." (PMID 26074734, 2015). "As expected, these molecules sensitize a variety of tumor cell lines to the BCL-2/BCL-XL inhibitor navitoclax." (PMID 25590800, 2015).
tumor (continued). "Our results suggest that activated CECs (Bcl-2-positive) were released from primary tumors and they co-migrated with tumor cells to distal sites." (PMID 26509633, 2015). "miR-204 expression and its role has been studied in some solid tumors: pancreatic, gastric, prostate, in which it acts by down-regulation of Bcl-2 and has tumor suppressor role." (PMID 26126974, 2015). "Bcl-2 overexpression in endothelial cells (EC-Bcl-2) significantly enhanced adhesion molecule expression and tumor cell binding that was predominantly mediated by E-selectin." (PMID 26509633, 2015). "We found that basal levels of other cancer-related KEAP1 targets, IKKβ and BCL2, were elevated in Keap1-/- MEFs and in human tumor lines with high basal NRF2 activity." (PMID 26301506, 2015). "The only RNA replacement clinical trial to date began in April 2013 as a strategy to deliver miR-34, a tumor-suppressive miRNA that regulates expression of BCL-2 and MYC, to patients with liver-based cancers." (PMID 25849966, 2015). "Bax and Bcl-2 are the major members of Bcl-2 family whose play a key role in tumor progression or inhibition of intrinsic apoptotic pathway triggered by mitochondrial dysfunction." (PMID 25864810, 2015). "Our results demonstrate that apigenin alters the Bax/Bcl2 ratio to shift in favor of apoptosis in tumor cells." (PMID 26379052, 2015). "A direct consequence of MTOB-inhibited GDH activity decreased Bcl-2 level, which indicates the increased tumor cell apoptosis." (PMID 25633289, 2015). "Because bcl-2, bcl-xL, survivin, and IAP-1/2 have been implicated in tumor cell survival and mitochondrial dysfunction, we next examined the effects of ART on the constitutive expression of these mRNA and proteins." (PMID 25738364, 2015). "We further observed that expression of BCL2 is frequently increased in the tumor samples of the TCGA dataset when compared to the matched samples." (PMID 26575290, 2015). "We analyzed the relationship between the co-expression of the p38 or p-p38 and Bcl-2 expression in tumor tissues." (PMID 26475474, 2015). "Here, we demonstrated that HNHA produced more powerful anti-tumor effects than SAHA and TSA in PTC and ATC cells in vitro and in vivo, by causing apoptosis via inhibition of Bcl-2 and modulation of the cell cycle G1/S checkpoint signaling pathway." (PMID 26698299, 2015). "The IHC result showed that administrating YSC-ZDC increased Bax protein level and decreased Bcl-2 protein level in tumor tissue." (PMID 26089933, 2015). "In conclusion, As2O3 nanoparticles, prepared using the sol-gel method, were found to produce a stronger cytotoxic effect on tumor cells than that produced by the As2O3 solution, possibly by inhibiting Bcl-2 expression." (PMID 26622477, 2015). "Almost 75% of CD5+ DLBCL patients had concurrent overexpression (≥70% of the tumor cells) of antiapoptotic Bcl-2, an unfavorable biomarker." (PMID 25760242, 2015). "ABT-199 (venetoclax), a second-generation, rationally designed inhibitor that was re-engineered to bind selectively to BCL-2, shows anti-tumor activity in primary tumor cells and xenograft models." (PMID 26537004, 2015). "In multivariable analysis, factors associated with shorter DMFS varied according to molecular subtype, with tumor size being associated with shorter DMFS in the LBH−, LBH+ and TN groups and the Rho GEF Trio and BCL2 phenotypes in TN tumors only." (PMID 26405647, 2015). "In fact, in vitro the restoration of these miRNA levels down-regulated Bcl-2 and Notch1/2 stemness genes and reduced in vitro the inhibition of tumor sphere (tumor stem cell colonies) formation reducing tumor growth in pancreatic cancer cell engraftment." (PMID 26259238, 2015). "The PI3K/Akt signaling pathway is activated in numerous cancers and plays important roles in tumor progression by phosphorylating various substrates such as mTOR, BCL-2, FoxO-family transcription factors, among others." (PMID 25714026, 2015).
tumor (continued). "Endothelial cells overexpressing Bcl-2 showed (EC-Bcl-2) significantly higher binding to tumor cells (CAL27 and UM-SCC-74B) as compared to vector control cells." (PMID 26509633, 2015). "By contrast, SCL treatment decreased Bcl-2 expression and increased Bax expression of H22 tumor tissues in a dose-dependent manner." (PMID 26426041, 2015). "Nine out of twelve (75%) tumour samples stained positive for bcl-2 throughout basal and parabasal layers, with most of cells showing strong cytoplasmic immunoreactivity." (PMID 25601891, 2015). "Expression of the anti-apoptotic BCL2 protein should contribute to resistance to cisplatin-induced tumor cell apoptosis and thus lead to a poor response and outcome." (PMID 26656462, 2015). "Cisplatin and AC likely synergize in several ways through increasing pro-apoptotic Bax, decreasing anti-apoptotic Bcl-2 as well as overexpressing caspase genes 3, 8 and 9 to protect mice from the challenge of line-1 tumor cells." (PMID 26325335, 2015). "Among the numerous available small molecule BH3 mimetics, ABT-737, a potent small molecule that binds to Bcl-2/Bcl-xL with high affinity, has anti-tumor activity in a wide variety of cancer cells." (PMID 26447615, 2015). "Tumor cells use several pathways to suppress apoptosis and acquire resistance to apoptotic agents, such as via expression of antiapoptotic proteins like Bcl-2." (PMID 26170886, 2015). "Bcl-2 is overexpressed in many cancers and contributes to tumor initiation, progression and resistance to therapy." (PMID 26472348, 2015). "We first confirmed that BCL2 is significantly overexpressed at the mRNA and protein levels in HOXA9-positive cells, which was consistent with increased levels of BCL2 protein in HOXA9-expressing subcutaneous tumor." (PMID 25762636, 2015). "To date, only a limited number of tumor-related prognostic parameters exist for DLBCL like presence of C-MYC rearrangements or co-expression of bcl2 and c-myc." (PMID 26071053, 2015). "Our findings provide a novel potential mechanism through which Bcl-2 boosts tumor cell proliferation in part due to the downregulation of lncRNA PANDAR, which releases the NF-YA." (PMID 25719249, 2015). "We assumed that TNF-α also plays an important role in the process of SCL-induced apoptosis in H22 tumor cells, via regulation of the expression of Bcl-2 and Bax." (PMID 26426041, 2015). "Paclitaxel directly induces apoptosis of several types of tumor cells through a variety of mechanisms, such as phosphorylation of Bcl-2, activation of caspase-3 and caspase-9, and the mitogen-activated protein kinase signal transduction pathway." (PMID 26223974, 2015). "Previous reports have showed that MMP–2, Bcl–2 and Mcl–1 are direct targets of miR-29a in regulating tumor progression in different cancer cells." (PMID 26441331, 2015). "To assess the effect of CQ on tumor cell apoptosis, we performed Western blot analysis of Bax and Bcl-2, and the Bax/Bcl-2 ratio was calculated." (PMID 25923669, 2015). "Bcl-2 positivity was significantly correlated with smaller tumor size, lower grade, ER positivity, PR positivity, and HER2 negativity, in both groups with and without tamoxifen therapy." (PMID 26472348, 2015). "Similar to cytoplasmic Survivin, Bcl-2 inhibits the proapoptotic functions of Bax and promotes cellular proliferation, which is ultimately reflected in the biological tumor behavior of each type of AM." (PMID 25866434, 2015). "In FL B cells, forced Bcl-2 expression protects tumor cells from apoptosis, but B cell survival factors released by FDC and T cells are still important for FL B cells persistence." (PMID 25815348, 2015).
tumor (continued). "Enhanced transcription and expression of Bcl2 increases B cell survival and is important for maintenance and progression of tumours." (PMID 25680182, 2015). "The clinical outcome of tumor tissues co-expressing p38/p-p38 and Bcl-2 were analyzed by Kaplan Meier." (PMID 26475474, 2015). "Previous studies have reported that TNF-α significantly increased the Bax genes, but significantly decreased the Bcl-2 gene level in in human tumor cells." (PMID 26426041, 2015). "It was notable that the combined treatment caused significantly increased levels of caspase 3, 8 and 9 activity, and that an increased expression ratio of Bax/Bcl-2 was also observed in the tumor tissues." (PMID 26622796, 2015). "There are researches which show that Bcl-2 protein is involved in cellular process besides apoptosis which influences the progression of tumor." (PMID 26494988, 2015). "High expression of Bcl-2 and low expression of Bax were observed in the tumor tissue sections of the model group." (PMID 26426041, 2015). "In a PANC-1 xenograft mouse model, we further demonstrated that the combination of metformin and aspirin significantly inhibited tumor growth and downregulated the protein expression of Mcl-1 and Bcl-2 in tumors." (PMID 26056043, 2015). "Mechanistic investigations reveal that a miR-197-mediated CKS1B/STAT3 axis exerts tumor progression regulated by various oncogenic genes (Bcl-2, c-Myc, and cyclin D1), and PD-L1 is a putative biomarker of this axis." (PMID 25597412, 2015). "Bcl-2 plays an anti-apoptotic role, resulting in poor clinical outcome or resistance to therapy in most tumor types expressing Bcl-2." (PMID 26472348, 2015). "The Bcl-2 and Survivin proteins are involved in the inhibition of apoptosis processes and possibly play roles in cellular proliferation, tumor progression, aggressive clinical behavior, and oncogenesis of the odontogenic epithelium." (PMID 25866434, 2015). "The expression of Bcl-2 was reduced whereas the expression of Bad, Bax, and Bak was found to be higher in tumor samples treated with these drugs." (PMID 26451606, 2015). "Previous studies have suggested that miR-29b exerts its tumor-suppressing function by targeting oncogenes such as Bcl-2, Mcl-1, and MMP-2." (PMID 26512921, 2015). "It has been reported that curcumin can successfully restore the phosphorylation and activation of the JAK3-STAT5a pathway in T cells and activation of this pathway restores the level of BCL-2, thus reducing T cell apoptosis in tumor-bearing mice." (PMID 26464579, 2015). "Navitoclax and the BCL-2-selective inhibitor venetoclax are also being tested in the clinic, where they are demonstrating anti-tumor activity in hematological cancers." (PMID 25590800, 2015). "Our results show that endothelial cells overexpressing Bcl-2 (EC-Bcl-2) expressed significantly higher levels of E-selectin and exhibited enhanced tumor cell binding." (PMID 26509633, 2015). "Consistent with IHC result, western blot data showed that YSC-ZDC dose-dependently increased Bax protein level and decreased Bcl-2 protein level in tumor tissue." (PMID 26089933, 2015). "During tumorigenesis, overexpression of CypD inhibits cell death induction in tumor cells due to interactions with cell death proteins, such as anti-apoptotic Bcl-2 and hexokinase II." (PMID 25879199, 2015). "The mRNA level of Bcl-2 decreased after treating the tumor-bearing mice with cisplatin, while that of Bax increased instead." (PMID 26325335, 2015). "Clotrimazole also markedly reduced Bcl-2 expression and increased the protein level of Bax in tumor tissues of xenograft model." (PMID 24892421, 2014).
tumor (continued). "The suppression of PAX8 was associated with a reduction in both cell growth and BCL2, suggesting that a reduction in PAX8 expression would sensitise tumours to cell death." (PMID 24602166, 2014). "Overexpression of Bcl-2 in tumor cells can produce tolerance to a variety of anticancer drugs and mediate escape from cell death." (PMID 25177684, 2014). "Cyclooxygenase-2 (COX-2) and B-cell lymphoma-2 (Bcl-2) overexpression has recently been reported as a potential tumor initiator or promoter." (PMID 24387269, 2014). "ABT-737 and ABT-263 have been shown to induce apoptosis in tumor cells by disrupting the interactions between anti- and pro-apoptotic Bcl-2 proteins." (PMID 24901320, 2014). "This is in agreement with our previous study, which indicated that metallic nickel nanoparticles elicited higher activation of tumor promotion factors phospho-Akt and Bcl-2 than fine particles." (PMID 24691273, 2014). "Bcl2 is a cellular protooncogene that functions as a potent antiapoptotic molecule and tumor promoter." (PMID 24967145, 2014). "Increased BCL-2 protein in tumor cells stabilizes mitochondrial membrane and prevents the release of cytochrome c from mitochondria, consequently interrupting the intrinsic apoptotic signaling cascade." (PMID 25231749, 2014). "Cisplatin treatment was shown to induce apoptosis, grossly observed by reduced tumor formation, through reduced Bcl-2 and survivin protein expression levels with an increase in caspase 3 expression compared to control tumors." (PMID 23755153, 2014). "The induction of apoptosis in tumor cells has been proposed to result from the inability of Bcl-2 to form heterodimers with Bax." (PMID 24348867, 2014). "We also performed exploratory analyses to assess the relationship between vitD and biomarkers of tumor biology, including Ki67, tumor grade, and Bcl2 phosphorylation." (PMID 24719175, 2014). "The miR-15a/16 cluster, for example, is well known to act as a tumor suppressor by targeting multiple oncogenes, including BCL2, MCL1, CCND1 and WNT3A, whereas the miR-17/92 cluster is recognized as an oncogene." (PMID 24520312, 2014). "We have also found the higher percentage of BCL-2-positive tumours among luminal A and B cancer immunophenotypes as compared with HER2+ and TN immunophenotypes." (PMID 25005788, 2014). "Tamoxifen treatment significantly altered the hormone receptor expression levels of the tumor, while additionally upregulating Bcl-2 and Cyclin D1." (PMID 23755153, 2014). "Positively charged chitosan coated PLGA nanoparticles with siRNA increased transfection and blocked the expression of anti-apoptotic Bcl-2 gene with significant cellular uptake and tumor regression." (PMID 25071577, 2014). "Other studies of Coix seed extract show that it can inhibit tumor cell mitosis at G2/M phases, induce tumor cell apoptosis, inhibit tumor angiogenesis, and also upregulate FASN/Apo-1 gene expression and downregulate Bcl-2 gene expression of tumor cells." (PMID 24778702, 2014). "Increased levels of Bcl-2 protein is observed in many tumor cells, contributes to increased tumor cell resistance and tumor growth by decreasing Bax-Bcl-2 ratio." (PMID 25663820, 2014). "Based on the data of our study, we conclude that the Pan-Bcl-2 inhibitor Obatoclax counteracts various biological processes relevant for tumor progression." (PMID 25192188, 2014). "It has also been shown to induce tumor cell death by affecting the expression/activity of multiple cancer-specific targets, including downregulation of the antiapoptotic protein Bcl-2 and upregulation of the proapoptotic protein Bax." (PMID 24722580, 2014). "We therefore measured the effects of embelin on the expression of cell cycle proteins (Cyclin D1, CDK-2, and CDK-6), and Bcl-2 family members (Bcl-2, and Bax) in tumor tissues by Western blot analysis and immunohistochemistry." (PMID 24694877, 2014).